UBA1 (ubiquitin like modifier activating enzyme 1)
Diseases named in the same sentence as UBA1 in open-access papers (continued):
Sharing a sentence is not in itself a finding about the gene and the disease.
leukemia (10 papers, 2013 to 2025). A malignant (clonal) hematologic disorder, involving hematopoietic stem cells and characterized by the presence of primitive or atypical myeloid or lymphoid cells in the bone marrow and the blood. "In order to understand the broader genomic context of putative somatic UBA1 variants in myeloid malignancies, we searched for chromosomal aberrations and co-mutations in known leukemia driver genes." (PMID 36823397, 2023). "It has been reported that UBA1 silencing or pharmacologic inhibition of UBA1 causes cell death in myeloma and leukemia cell lines and primary leukemia cells, and delays tumor growth in SCID mice from leukemia xenografts." (PMID 29152096, 2017). "The observed pattern underscores the low-risk nature of M41 mutations and aligns with preclinical evidence suggesting the anti-leukemia efficacy of UBA1 inhibitors." (PMID 41068485, 2025). "Furthermore, silencing UBA1 reduced the abundance of ubiquitinated proteins in leukemia and myeloma cells and promoted cell death, and in mouse models of leukemia and multiple myeloma, inhibiting UBA1 expression strikingly diminished tumor weight and volume." (PMID 33344241, 2020). "A study has found that leukaemia cell lines and primary acute myeloid leukaemia (AML/LAML) samples have an increased dependence on UBA1 and a decreased enzyme reserve capacity, indicating that inhibiting UBA1 may be valuable in the treatment of AML." (PMID 39183260, 2024). "But UBA1 protein levels in leukemia cells and normal cells are not different by immunoblotting." (PMID 23915341, 2013).
autoinflammatory syndrome (8 papers, 2022 to 2025). A group of disorders of the innate immune system characterized by attacks of seemingly unprovoked inflammation without significant levels of either autoantibodies or autoreactive T cells more characteristic of autoimmune disease. "VEXAS (Vacuoles, enzyme E3, X-linked, Autoinflammatory, Somatic) is a recently reported late-onset autoinflammatory syndrome characterized by myeloid lineage-restricted somatic mutations in the ubiquitin-activating E1 (UBA1) gene." (PMID 39810778, 2025).
lung carcinoma (8 papers, 2008 to 2025). "To assess the potential importance of UBA1 and/or UBA7 in asbestos-associated lung cancer or lung carcinomas in general we measured the protein levels in normal and tumour tissue samples of 12 lung cancer patients (data not shown)." (PMID 19014429, 2008). "In contrast to gene expression, the protein level of UBA1 was more strongly expressed in lung cancer, suggesting UBA1 may preferentially enhance its ubiquitination properties within the lung cancer microenvironment, thereby modulating its own stability." (PMID 40046044, 2025). "Additionally, the abnormal expression of UBA1, an E1 enzyme for ubiquitin-activating enzymes, is associated with lung cancer (LC) and cutaneous squamous cell carcinoma (SCC), revealing the potential value of UBA1 as an HCC diagnostic and prognostic marker." (PMID 33344241, 2020). "In addition, previous studies have shown that the abnormal expression of UBA1 is related to the malignant phenotype of lung cancer (LC), liver cancer, colorectal cancer and other diseases, and can be used as a potential marker for cancer diagnosis and prognosis." (PMID 40046044, 2025). "Recently, somatic mutations of the UBA1 gene were identified in patients with vacuoles, E1 enzyme, X-linked, autoinflammatory, somatic (VEXAS) syndrome in males and lung cancer in never-smokers (LCINS) in females." (PMID 39762237, 2025). "The GAPDH-scaled protein expression levels of UBA1 and UBA7 were compared between the exposed and non-exposed lung cancer patients, separately for the normal and tumour tissue samples." (PMID 19014429, 2008).
macrocytic anemia (7 papers, 2024 to 2026). Anemia that is characterized by increased red blood cell volume. "Among the included variables, only cutaneous lesions, chondritis, and macrocytic anemia were significantly more prevalent in participants with UBA1 variants." (PMID 41026267, 2025). "Thus, features such as skin involvement, unintended weight loss, inflammation, and signs of macrocytic anemia were associated with UBA1 variants in our primary cohort." (PMID 41026267, 2025). "The two patients with the UBA1 somatic mutation identified by Sanger sequencing (RP09 and RP13) were older men with macrocytic anemia." (PMID 38167209, 2024). "Macrocytic anemia/macrocytosis and vacuoles in myeloid/erythroid precursors are prominent features of VEXAS syndrome, and their presence in patients with autoinflammatory symptoms prompts physicians to screen for UBA1 variant." (PMID 38819628, 2025). "Clinical features of VEXAS such as fevers, skin involvement, macrocytic anemia, and arthralgias were prevalent with all pathogenic UBA1 variants, regardless of vacuolization status." (PMID 39415928, 2024). "It is worth noting that the third patient with a low VAF of UBA1 (RP34) did not exhibit macrocytic anemia, but did have macrocytosis." (PMID 38167209, 2024).
multiple myeloma (7 papers, 2017 to 2025). "Due to the absence of UBA1 mutations in lymphocytes and the demographic overlap, some believe that multiple myeloma develops independently of UBA1 mutations." (PMID 39347709, 2024). "Plasma cell dyscrasias, monoclonal B cell lymphocytosis, and multiple myeloma are common in VEXAS patients, even though VEXAS patients commonly exhibit B cell lymphocytopenia and their B cells rarely harbor the UBA1 mutations." (PMID 40394087, 2025).
glioblastoma (6 papers, 2021 to 2025). The most malignant astrocytic tumor (WHO grade IV). "GRP78 is also predictive of glioblastoma cells’ sensitivity to ubiquitin-like modifier activating enzyme 1 (UBA1) inhibitor TAK-243." (PMID 36358853, 2022). "In squamous cell carcinoma, cell lines with lower expression of UBA1 responded better to TAK-243, whereas in glioblastoma cell lines with lower expression of the ER chaperone GRP78 and not UBA1 expression responded better to TAK-243." (PMID 39347709, 2024). "Inhibition of the UBA1 leads to UPR and subsequent cell apoptosis, resulting in longer survival of glioblastoma-bearing mice." (PMID 36358853, 2022). "Glioblastoma had the greatest negative correlation between UBA1 and NEDD8 (R = −0.5184), consistent with reports showing up-regulation of NEDD8 in glioblastoma." (PMID 34685640, 2021).
Huntington disease (6 papers, 2015 to 2025). Huntington disease (HD) is a rare neurodegenerative disorder of the central nervous system characterized by unwanted choreatic movements, behavioral and psychiatric disturbances and dementia. "Lower levels of endogenous UBA1 in the brain also correlate with increased levels of mutant huntingtin protein in a mouse model of Huntington’s disease." (PMID 39773572, 2025). "Intriguingly, mutations of the ubiquitin-like modifier activating enzyme 1 (UBA1) gene, which disrupts the normal ubiquitinylation pattern, are associated with a rare X-linked SMA form and are implicated in other neurodegenerative diseases as well, such as Huntington’s chorea." (PMID 38727321, 2024).
relapsing polychondritis (6 papers, 2022 to 2026). A rare, clinically heterogeneous, multisystemic inflammatory disease characterized by inflammation of the cartilage and proteoglycan rich structures leading to cartilage damage with joint, ocular and cardiovascular involvement. "In turn, we have demonstrated that 73% (8/11) of the male patients with relapsing polychondritis had somatic UBA1 variants, showing that significant part of male polychondritis is associated with VEXAS syndrome." (PMID 38819628, 2025). "Commonly clinically diagnosed with relapsing polychondritis (RP), vacuoles, E1 enzyme, X-linked, autoinflammatory, somatic syndrome (VEXAS) is a recently identified autoinflammatory disease caused by UBA1 somatic mutations." (PMID 38167209, 2024). "All individuals with UBA1 variant (9 male, 2 female) had VEXAS-like rheumatologic and/or hematologic manifestations, but only 55% had the classical features diagnostic to VEXAS (e.g. relapsing polychondritis, polyarteritis nodosa, Sweet syndrome)." (PMID 38819628, 2025). "Prior to detecting UBA1 somatic mutations in blood, the majority of patients with VEXAS are diagnosed with relapsing polychondritis (RP), as well as a small number with other inflammatory diseases, such as giant cell arteritis, polyarteritis nodosa, and Sweet syndrome." (PMID 38167209, 2024).
anemia (5 papers, 2021 to 2026). A reduction in the number of red blood cells, the amount of hemoglobin, and/or the volume of packed red blood cells. "UBA1 should be sequenced in this population, especially in case of macrocytic associated anemia and chronically elevated CRP among old males, but not exclusively." (PMID 34884286, 2021). "For example, if diagnosed with MDS, patients carrying isolated UBA1 mutations classify as low-risk MDS, for which erythroid stimulating agents (ESA) and luspatercept, an erythroid maturation agent, may be used to manage anemia." (PMID 41068485, 2025).
autoimmune disorders (5 papers, 2021 to 2025). "Given its essential function in apoptotic cell clearance and that X-inactivation escape tends to increase with aging, UBA1 dysfunction can therefore predispose aging women to autoimmune disorders." (PMID 34373855, 2021). "For systemic inflammatory and autoimmune disorders associated with MDS/CMML, MDS EB, and MDS MLD were the most frequently associated subtypes in USAID patients not UBA1 mutated." (PMID 34884286, 2021).
breast carcinoma (5 papers, 2015 to 2026). "In the results of immunohistochemistry from The Hunam Protein Atlas, it was found that the expression of UBA1 in breast cancer was higher than that in controls." (PMID 39684409, 2024). "Nevertheless, the precise contribution of UBA1 in breast cancer (BC) is still poorly characterized." (PMID 39684409, 2024). "Data from The Human Protein Atlas alone are not enough to understand the function of UBA1 protein in breast cancer, as the protein is the agent of function." (PMID 39684409, 2024). "Moreover, due to limitations, we were not able to obtain enough clinical samples of breast cancer to detect the UBA1 protein levels." (PMID 39684409, 2024).
hepatocellular carcinoma (5 papers, 2020 to 2024). A malignant tumor that arises from hepatocytes. "Previous studies have associated abnormal UBA1 expression with the progression of hepatocellular carcinoma (HCC), small-cell lung cancer (SCLC), and cutaneous squamous cell carcinoma (SCC)." (PMID 39684409, 2024). "As suggested in this study, UBA1 serves as a possible marker for diagnosis and prognosis prediction and regulates hepatocellular carcinoma (HCC) cell proliferation, invasion, migration, and ferroptosis through the Nrf2 signal transduction pathway." (PMID 33344241, 2020). "Ubiquitin-like modifier-activating enzyme 1 (UBA1) is a potential marker for hepatocellular carcinoma (HCC) prognosis since its expression positively correlates with survival rate." (PMID 34485285, 2021). "Thirdly, in hepatocellular carcinoma tissues, enzymes involved in the ISGylation process (including EFP, HERC5, UBA1 and USP18) are elevated compared with adjacent non‐tumour tissues." (PMID 36071546, 2022).
liver cancer (5 papers, 2020 to 2025). An epithelial or non-epithelial malignant neoplasm that arises from the liver. "The high expression of UBA1 is associated with poor prognosis of liver cancer patients." (PMID 37417208, 2023). "Through this meticulous analysis, UBA1 was identified as a unique biomarker for liver cancer diagnosis and prognosis." (PMID 40109873, 2025). "UBA1 knockdown inhibited proliferation, migration, and invasion of liver cancer cells." (PMID 37417208, 2023). "According to our findings, UBA1 might play a vital role during liver cancer development." (PMID 33344241, 2020). "In conclusion, our study shows that expression of EFP, HERC5, UBA1 and USP18 genes, upregulated in tumour tissues of HCC patients, is correlated with liver function parameters and, thus, may be associated with the pathogenesis of liver cancer." (PMID 32132870, 2020). "We validated the expression level of UBA1 in eight pairs of HCC patient tissues and liver cancer cell lines." (PMID 33344241, 2020).
viral infection (5 papers, 2020 to 2025). "Ubiquitin activating enzyme (UBA1) interacts with TrAP protein and silencing of UBA1 promotes early viral infection in transgenic N. benthamiana." (PMID 34243802, 2021). "Thus, it is conceivable that UBA1 inhibitors may exacerbate the potential neurological damage in the context of a neurotropic viral infection." (PMID 39773572, 2025).
colon cancer (4 papers, 2017 to 2025). "Analysis using random forest method identified UBA1 as a key gene associated with colon cancer progression, and this finding was confirmed in tumor tissue samples using Immunohistochemistry (IHC) analysis." (PMID 37417208, 2023). "First, functional validation of the identified PLEGs and UBA1 in colon cancer was limited, and further experimental studies are needed to confirm their roles in tumorigenesis and progression." (PMID 37417208, 2023). "Among the PLEG, UBA1 plays a prominent role in promoting the malignant progression of colon cancer cells." (PMID 37417208, 2023). "By utilizing random forest analysis on six PLEG, UBA1 was determined to be the gene with the highest significance in distinguishing between colon cancer tissues and healthy tissues." (PMID 37417208, 2023). "This suggests that both UBA1 mRNA and protein expression levels are higher in colon cancer tissues when compared to normal colon tissues." (PMID 37417208, 2023). "Cell functional experiments demonstrated that knocking down UBA1 can inhibit the proliferation, invasion, and migration abilities of colon cancer cells." (PMID 37417208, 2023). "Immunohistochemistry results revealed that UBA1 protein is significantly upregulated in colon cancer tissues." (PMID 37417208, 2023). "Our findings revealed a significant increase in UBA1 protein expression in 30 colon cancer tissues when compared to their paired adjacent normal tissues." (PMID 37417208, 2023). "Next, the GSEA method was employed to identify differentially activated pathways in colon cancer with high UBA1 expression." (PMID 37417208, 2023). "The silencing of UBA1 has been shown to inhibit the proliferation, migration, and invasion of colon cancer cells." (PMID 37417208, 2023). "UBA1 inhibition in HCT116 human colon cancer cells results in cell death and UBA1 knockdown inhibits tumor growth from HCT116 xenografts." (PMID 29152096, 2017). "Random forest analysis showed that UBA1 is a key PLEG in the progression of colon cancer." (PMID 37417208, 2023). "Finally, the study evaluated the effects of UBA1 knockdown on colon cancer cell proliferation, invasion, and migration." (PMID 37417208, 2023). "Additionally, we have uncovered evidence supporting the pivotal role of UBA1 in the onset and progression of colon cancer." (PMID 37417208, 2023). "In the study, the expression level of UBA1 was found to be strikingly upregulated in colon cancer." (PMID 37417208, 2023). "Additionally, high expression of UBA1 and SEC61A1 were associated with a poorer prognosis in colon cancer patients." (PMID 37417208, 2023). "However, the biological role of UBA1 is less well understood in colon cancer." (PMID 37417208, 2023). "Thus, UBA1 is an independent indicator for colon cancer progression." (PMID 37417208, 2023). "This suggests that UBA1 may play a pivotal role in the progression of colon cancer." (PMID 37417208, 2023).
plasma cell dyscrasia (4 papers, 2022 to 2025). "However, plasma cell disorders are rarely associated with patients with chondritis, and hence the somatic variants of UBA1 should be screened in such patients." (PMID 35757758, 2022). "However, it is unclear whether somatic UBA1 variants induce the development of MM or whether pathological conditions, such as MGUS or plasma cell disorders, could arise from somatic UBA1 variants." (PMID 35757758, 2022). "However, plasma cell dyscrasias and monoclonal B cell lymphocytosis are observed in patients despite decreased B-lineage cells and the absence of UBA1 mutations in those cells." (PMID 40394087, 2025). "A strong association exists between UBA1 variants and the risk of MDS; however, it remains elusive whether somatic UBA1 variants contribute to the development of plasma cell dyscrasia without MDS." (PMID 35757758, 2022).
prostate carcinoma (4 papers, 2017 to 2025). A carcinoma that arises from epithelial cells of the prostate gland. "Of note, UBA1 was also frequently gained in many cancer types other than prostate cancer, whereas UBA1 mutations in cancers were rare." (PMID 39540840, 2025). "However, high expression of UBA1 is associated with good prognosis in prostate cancer patients." (PMID 37417208, 2023). "In prostate cancer cohorts, UBA1 exhibited frequencies of copy number gain higher than 40%, and importantly, the copy number of UBA1 was strongly correlated with its mRNA expression." (PMID 39540840, 2025). "We thus established two murine syngeneic models, the prostate cancer Myc-CaP model and melanoma B16-BL6 model, with engineered overexpression of Uba1." (PMID 39540840, 2025). "We next examined the correlation between expression of UBA1 and IFNG or CD8+ T cell–related signatures in cancer types other than prostate cancer." (PMID 39540840, 2025).